PNPLA3 (patatin like domain 3, 1-acylglycerol-3-phosphate O-acyltransferase )
Diseases named in the same sentence as PNPLA3 in open-access papers (continued):
Sharing a sentence is not in itself a finding about the gene and the disease.
ovarian dysfunction (1 paper, 2023). The inability of the ovaries to function. "Among the genes we identified through coexpression of three datasets, PNPLA3, MVD, MMP9, oncostatin M (OSM), LCK, triggering receptor expressed on myeloid cells 1 (TREM1), FADS2, proprotein convertase subtilisin/kexin type 9 (PCSK9), and C3 are involved in lipid metabolism and ovarian dysfunction." (PMID 37537636, 2023).
overnutrition (1 paper, 2021). An imbalanced nutritional status resulting from excessive intake of nutrients. "Overnutrition and sedentary lifestyle have been considered as the main causes of NAFLD and genetic variants, including PNPLA3 rs738409, TM6SF2 rs58542926 and HSD17B13 rs72613567, in patients may accelerate or decelerate the progression of NAFLD." (PMID 33728819, 2021).
pancreas disease (1 paper, 2012). "The current study examines the influence of PNPLA3 variant p.I148M in a large cohort of patients with alcoholic liver and pancreas disease and controls." (PMID 22276112, 2012).
pancreatic cancer (1 paper, 2021). "Therefore, it is considerable that stromal PNPLA3 I148M variant assists pancreatic cancer metastasis." (PMID 34503201, 2021). "Yet, it has not been clarified whether PNPLA3 rs738409 genetic variation is associated with the incidence or prognosis of pancreatic cancer patients." (PMID 34503201, 2021).
peritonitis (1 paper, 2023). Inflammation of the peritoneum (tissue that lines the abdominal wall and covers most of the organs in the abdomen). "Of note, liver patatin-like phospholipase domain–containing 3 (Pnpla3) showed the largest effect size among the detected transcripts in VX as compared with sham-treated mice with zymosan-induced peritonitis." (PMID 36997988, 2023).
Pruritus (1 paper, 2014). Pruritus is an itch or a sensation that makes a person want to scratch. "Moreover, our study identifies this PNPLA3 variant as potential genetic marker for therapy-refractory pruritus." (PMID 25297933, 2014). "Since the PNPLA3 allele p.148Ile may to a certain extent explain the development of therapy-refractory pruritus, genotyping of the PNPLA3 variant p.Ile148Met might be included in the diagnostic work-up of patients with cholestatic liver conditions." (PMID 25297933, 2014).
psoriasis (1 paper, 2022). An autoimmune condition characterized by red, well-delineated plaques with silvery scales that are usually on the extensor surfaces and scalp. "For PNPLA3, the age and sex adjusted odds ratio of psoriasis was 1.01 (0.90-1.15) in IM-heterozygotes and 1.04 (0.80-1.35) in MM-homozygotes compared to non-carriers." (PMID 36353626, 2022). "Subsequently, we used the genetic variants PNPLA3 and TM6SF2, both strongly associated with NAFLD and high liver fat content, to test whether NAFLD was causally associated with increased risk of psoriasis." (PMID 36353626, 2022). "In genetic analyses, PNPLA3 and TM6SF2 were both associated with increased risk of NAFLD but not with increased risk of psoriasis." (PMID 36353626, 2022).
renal fibrosis (1 paper, 2025). A final common manifestation of a wide variety of chronic kidney diseases characterized by glomerulosclerosis and tubulointerstitial fibrosis. "In this study, the patients with renal fibrosis included may carry a genetic variant of PNPLA3, which could influence the measured AUC value associated with PNPLA3." (PMID 41049486, 2025).
skin infection (1 paper, 2025). An inflammatory process affecting the skin, caused by bacteria, viruses, parasites, or fungi. "Notably, the main inherited risk variant for MASLD/MASH in the PNPLA3 gene underlying this heterogeneity has been associated with increased hepatic secretion of proinflammatory cytokines, reduced susceptibility to some skin infections and to severe COVID‐19." (PMID 40072231, 2025).
ulcerative colitis (1 paper, 2018). An inflammatory bowel disease involving the mucosal surface of the large intestine and rectum. "The effects of the PNPLA3 (P = 0.38) or TM6SF2 (P = 0.58) variants were also neither apparent in patients with nor in patients without ulcerative colitis (n = 55 and n = 123, respectively)." (PMID 30161167, 2018). "No impact of PNPLA3 or TM6SF2 risk variants was detectable in patients with PSC and ulcerative colitis, and none of the variants increased the odds of transplantation." (PMID 30161167, 2018). "PNPLA3 and TM6SF2 genotypes in PSC patients with and without ulcerative colitis." (PMID 30161167, 2018).
cancer (19 papers, 2013 to 2025). A tumor composed of atypical neoplastic, often pleomorphic cells that invade other tissues. "We found that drugs currently in clinical trials for cancer treatment that target the same pathways also reduced lipid accumulation in PNPLA3 variant cells." (PMID 39000384, 2024). "Although the PNPLA3 rs738409 variant G allele is undoubtedly more frequent in cancers compared to controls, there was also a significant difference between the cirrhotic versus the non-cirrhotic cases with NAFLD-HCC (p < 0.0001)." (PMID 33808740, 2021). "A variant in the patatin-like phospholipase domain-containing protein 3 gene (PNPLA3) is associated with increased liver fat, fibrosis, and risk for carcinoma, with a higher prevalence of the at-risk allele in Hispanic youth." (PMID 33081177, 2020). "We demonstrated that a series of small molecules and drugs, which are currently in clinical trials for the treatment of cancer, that target Src/PI3K/Akt could inhibit lipid accumulation in PNPLA3 variant hepatocytes." (PMID 39000384, 2024). "Since the PNPLA3 SNP has been previously associated with the development of HCC, further studies in patients with HCC are needed to assess whether an association between the SREBP1c variant and cancer susceptibility exists." (PMID 24152445, 2013). "Next, we treated the HepG2 human cancer cell line with C75 and found that FASN expression and the expression levels of liver‐specific genes, including PKLR, PNPLA3, and PCSK9, were significantly decreased after 24 h." (PMID 28827398, 2017). "In addition, according to literature evidence, HCC patients display an increased frequency distribution of PNPLA3 variant (29% MM vs. 16%; p < 0.0001 at one-way ANOVA) compared to NAFLD patients without cancer." (PMID 33917919, 2021).
cardiovascular disease (19 papers, 2012 to 2025). "They found that the MBOAT7 T allele decreased the mortality rate of cardiovascular disease together with PNPLA3 and TM6SF2 gene variants." (PMID 37424875, 2023). "TM6SF2 rs58542926 and PNPLA3 rs738409 were both associated with reduced serum triglyceride concentrations and a lower risk of cardiovascular disease, and there was probably a synergistic interaction." (PMID 35881683, 2022). "It is reasonable to postulate that individuals with a deletion in the PNPLA3 gene may face an elevated susceptibility to cardiovascular disease." (PMID 38523778, 2024). "PNPLA3 rs738409 and TM6SF2 rs58542926 both contributed to the reduced serum triglyceride levels and the decreased risk of cardiovascular disease." (PMID 35881683, 2022). "For example, while variants in genes such as PNPLA3 and TM6SF2 strongly predispose to MASLD, they may even protect against hyperlipidemia and cardiovascular disease." (PMID 39774697, 2025). "This novel finding helps to explain the strong association between the rs738409 SNP and NAFLD that has been largely and repeatedly demonstrated and raises new questions about the function of the PNPLA3 itself as well as about its potential implications in the development of cardiovascular diseases." (PMID 22629460, 2012). "The gene symbols like HABP2, PLG, PNPLA3, and TM6SF2 exhibit specific expression in hepatic tissue, and our study also suggests their potential impact on cardiovascular disease." (PMID 38523778, 2024).
metabolic disorders (13 papers, 2015 to 2025). "In this study, we identified four key genes, including FADS1, FADS2, GLB1, and PNPLA3, associated with both metabolic disorders and inflammation in MAFLD through bioinformatics methods." (PMID 41007773, 2025). "Notably, the ileal lncRNA NONMMUT040618 and its target mRNAs (Pxmp4, Pnpla3, and Car5a), which were involved in lipid and amino acid metabolism-related pathways, might play vital roles in the remission of metabolic disorders after DJB." (PMID 35464075, 2022). "Further evidence on the association between NAFLD and CKD, independent of metabolic diseases, may come from the reported association between PNPLA3 rs738409 G variant and CKD." (PMID 34680486, 2021). "The CKD group had more severe metabolic disorders, and also had higher prevalences of liver steatosis, the PNPLA3 rs738409 non-CC genotype, and the TM6SF2 rs58542926 CC genotype (all P < 0.05)." (PMID 37400794, 2023). "Possibly due to overexpression of PNPLA3 parenchymal and nonparenchymal cell interactions starts and may affect features of metabolic disorder through lipid accumulation and modulating fat content in NASH condition." (PMID 40017524, 2025).
tumor (8 papers, 2011 to 2025). "Additionally, we also investigated the relationship between PNPLA3 gene polymorphisms and serum tumor markers." (PMID 36447249, 2022). "In contrast, the expression levels of PNPLA3 and SARDH were significantly elevated in the tumor group compared to the control group, while ADSL expression was notably reduced in tumor tissues." (PMID 40313243, 2025). "qRT-PCR validation showed up-regulation of PNPLA3 and SARDH, and down-regulation of ADSL, in tumor tissues." (PMID 40313243, 2025). "HSD17B13, TM6SF2, PNPLA3, MTARC1, and HLA-DP1 exhibited lower expression in HCC compared with non-tumor liver tissues." (PMID 40823170, 2025). "In addition, qRT -PCR validation revealed significant differences in the expression of PNPLA3, SARDH, and ADSL in the control and tumour groups." (PMID 40313243, 2025).
infection (6 papers, 2012 to 2025). The state of being infected such as from the introduction of a foreign agent such as serum, vaccine, antigenic substance or organism. "We observed an interaction between homozygosity for the PNPLA3 I148M variant and age at infection in determining fibrosis progression in CHC patients." (PMID 25171251, 2014). "As expected, silencing Mlxipl effectively down‐regulated the expression of its target genes including Fasn, Acaca, Elovl6, Scd1, Ptpn6 and Pnpla3 at 36 hours after Ad‐siMlxipl infection although their expression was restored to the control level at 72 hours." (PMID 31809000, 2020). "In this extended model, the association of PNPLA3 148M/M with FPR (estimate +0.08±0.03, p = 0.018), as well as the interaction with older age at infection (estimate +0.07±0.03, p = 0.021) remained unaffected." (PMID 25171251, 2014). "Our study is the first to show that the effect of PNPLA3 I148M on fibrosis progression in CHC is modulated by the age at infection." (PMID 25171251, 2014). "At the multivariate generalized linear model considering known determinants of FPR (age at infection, gender, and viral genotype: shown in model 1) PNPLA3 148M/M was an independent predictor of FPR (p = 0.022)." (PMID 25171251, 2014). "Effect of PNPLA3 148M/M on (log10) FPR in 247 CHC patients according to different thresholds of age at infection." (PMID 25171251, 2014). "Furthermore, there was a significant interaction between PNPLA3 148M/M and older age at infection in determining FPR (p = 0.025; estimate +0.07±0.03)." (PMID 25171251, 2014). "To test the robustness of the association between PNPLA3 genotype and FPR, we extended the model with further adjustment for additional potential confounders: age at biopsy, presence of overweight, and route of infection (model 2)." (PMID 25171251, 2014). "In this paper, we showed that in a prospective cohort with careful estimation of the date of infection and absence of major confounders the PNPLA3 I148M sequence variant influences fibrosis progression in CHC." (PMID 25171251, 2014). "At multivariate analysis, PNPLA3 148M/M was associated with FPR (incremental effect 0.08±0.03 log10 fibrosis unit per year; p = 0.022), independently of several confounders, and there was a significant interaction between 148M/M and older age at infection (p = 0.025)." (PMID 25171251, 2014). "Since PNPLA3 148M allele has been reported to influence lipid accumulation in the liver, it is possible to hypothesize that PNPLA3 148M allele may impair both viral and lipoprotein release from infected hepatocytes resulting in lower baseline plasma viral load in HCV genotype 2 infection." (PMID 22978414, 2012). "Three days after infection, PNPLA3 was readily detected in liver, but not in BAT." (PMID 41278711, 2025).
kidney disease (3 papers, 2015 to 2025). "Additionally, genetic variants such as PNPLA3, TM6SF2, and MBOAT7 were identified as contributing to both liver and kidney disease, increasing cardiometabolic risk." (PMID 40217935, 2025).
genetic disease (2 papers, 2019 to 2023). "NASH is also a genetic disease; certain genes—including those encoding patatin-like phospholipase domain-containing 3 (PNPLA3), transmembrane 6 superfamily 2 (TM6SF2), and glucokinase regulatory protein (GCKR)—have been implicated as predisposing to its progression to NASH." (PMID 31775341, 2019).
inflammation (2 papers, 2022 to 2025). Aberrant reaction of the microcirculation characterized by movement of fluid and leukocytes from the blood into extravascular tissues. "Antisense oligonucleotide (ASO)–mediated silencing of PNPLA3 in mice overexpressing the human PNPLA3 I148M reduced liver inflammation and fibrosis." (PMID 40589542, 2025). "SNPs in PNPLA3, TNF-α, AGTR1, IL-17A, IL-1B, PTPRD, and GATAD2A cause liver inflammation." (PMID 36000237, 2022).
liver (2 papers, 2011 to 2023). "Putting these data together with our results we speculate that the exposing role played by abdominal fat on the PNPLA3 polymorphism may be sustained by the close direct association between visceral fat and liver inflammation." (PMID 22140488, 2011). "Therefore, PNPLA3 genotypes may not be involved in simple fatty liver and relatively mild NASH without fibrosis." (PMID 37304843, 2023).
mitochondrial disease (1 paper, 2025). "Since MASLD occurs as a mitochondrial disease and the PNPLA3, MBOAT7 and TM6SF2 loss-of-function mutations seem to achieve a role in organelles’ dysfunction, in this study, we firstly investigated the impact of gene deletion on mitochondrial dynamism and integrity in KO HepG2 cells." (PMID 40563253, 2025).
PNPLA3 also shares sentences with these, for which no sentence is quoted: portal hypertension (4 papers); alcohol (3); asthma (3); viral infection (3); all (2); breast carcinoma (2); chronic hepatitis (2); COVID-19 (2); gallstones (2); Glucose intolerance (2); Hypercholesterolemia (2); non-alcoholic fatty liver (2); rheumatoid arthritis (2); acute kidney injury (1); Ascites (1); atransferrinemia (1); autoimmune conditions (1); basal cell carcinoma (1); biliary tract cancer (1); cataract (1); celiac disease (1); cholestasis (1); Cholestatic liver disease (1); chronic liver failure (1); dyslipidaemia (1); endocrine disorders (1); gastroesophageal reflux (1); glioma (1); hemochromatosis (1); hepatitis (1).
A further 19 diseases each share a sentence with PNPLA3 in 1 paper.